CYP3A7-CYP3A51P (CYP3A7-CYP3A51P readthrough)
Synonyms: CYP3A7-3AP1; CYP3A7-CYP3AP1; CYP3A7.1L
Gene: Protein-coding gene on chromosome 7 (99,684,957 to 99,735,102, reverse strand). Ensembl gene ENSG00000282301.
Genetic constraint (gnomAD): Loss-of-function variants: 43 observed, 56.38 expected, observed/expected ratio (o/e) 0.76, 90% interval 0.6 to 0.98. The upper end of that interval is the gene's LOEUF score, 0.98, which puts it in group 4 of 6, group 1 being the genes least tolerant of losing a copy. Missense variants: 543 observed, 622.23 expected, observed/expected ratio (o/e) 0.87, 90% interval 0.81 to 0.94. Synonymous variants: 175 observed, 211.21 expected, observed/expected ratio (o/e) 0.83, 90% interval 0.73 to 0.94.